TAS1R3 (taste 1 receptor member 3)
Description:
Putative taste receptor. TAS1R1/TAS1R3 responds to the umami taste stimulus (the taste of monosodium glutamate). TAS1R2/TAS1R3 recognizes diverse natural and synthetic sweeteners. TAS1R3 is essential for the recognition and response to the disaccharide trehalose (By similarity). Sequence differences within and between species can significantly influence the selectivity and specificity of taste responses.
Synonyms: T1R3
Tractability: Small molecule: it belongs to a druggable protein family. Antibody: its Gene Ontology location is reachable by antibodies, with high confidence; UniProt places it where antibodies can reach, with medium confidence; UniProt predicts a signal peptide or a membrane-spanning region; the Human Protein Atlas places it where antibodies can reach. PROTAC: a small molecule that binds it is known.
Target class: Membrane receptor; Taste receptor (family C GPCR); Family C G protein-coupled receptor
Gene: Protein-coding gene on chromosome 1 (1,331,280 to 1,335,314, forward strand). Ensembl gene ENSG00000169962.
Subcellular location: Cell membrane
Subcellular location (Human Protein Atlas): Plasma membrane; Golgi apparatus
Pathways (Reactome):
Signal Transduction: Class C/3 (Metabotropic glutamate/pheromone receptors); G alpha (i) signalling events
Sensory Perception: Sensory perception of sweet, bitter, and umami (glutamate) taste
Gene Ontology:
Molecular function: protein binding; sweet taste receptor activity; taste receptor activity; G protein-coupled receptor activity
Biological process: detection of chemical stimulus involved in sensory perception of sweet taste; sensory perception of sweet taste; sensory perception of umami taste; G protein-coupled receptor signaling pathway; sensory perception of taste
Cellular component: G protein-coupled receptor dimeric complex; plasma membrane; sweet taste receptor complex; membrane
Genetic constraint (gnomAD): Loss-of-function variants: 59 observed, 44.74 expected, observed/expected ratio (o/e) 1.32, 90% interval 1.07 to 1.64. The synonymous counts are far from expectation, so gnomAD's model fits this gene poorly and the ratio says little. Missense variants: 1,422 observed, 1,134.6 expected, observed/expected ratio (o/e) 1.25, 90% interval 1.2 to 1.31. Synonymous variants: 724 observed, 519.46 expected, observed/expected ratio (o/e) 1.39, 90% interval 1.31 to 1.48.
Homologues: Orthologues: chimpanzee TAS1R3 (99% identical), macaque TAS1R3 (91% identical), dog TAS1R3 (76% identical), pig TAS1R3 (75% identical), mouse Tas1r3 (73% identical), rat Tas1r3 (73% identical), guinea pig TAS1R3 (72% identical), zebrafish tas1r3 (36% identical). Paralogues in human: TAS1R1 (31% identical), GPRC6A (28% identical), TAS1R2 (28% identical), CASR (28% identical).
Diseases named in the same sentence as TAS1R3 in open-access papers:
TAS1R3 is named in the same sentence as 37 diseases in open-access papers, as found by Europe PMC text mining. Sharing a sentence is not in itself a finding about the gene and the disease. The quoted sentences say what the papers report.
Obesity (10 papers, 2014 to 2025). Accumulation of substantial excess body fat. "This in vitro study aims to measure the impact of human TAS1R2/TAS1R3 polymorphisms, some of which are thought to be involved in obesity, on the response of the sweet taste receptor to various sweeteners." (PMID 40289963, 2025). "Finally, our data suggested that factors other than the TAS1R2 and TAS1R3 SNPs were associated with obesity." (PMID 40289963, 2025). "Background/Objectives: Studies have hypothesised that single-nucleotide polymorphisms (SNPs) in the TAS1R2 and TAS1R3 genes may alter sweet compound detection and eating habits, thereby increasing the risk of obesity." (PMID 40289963, 2025). "It would also be possible to verify whether there are sensory and nutritional intake differences between mutation carriers of the TAS1R2 gene and the TAS1R3 gene to determine whether one of these genes is predominantly involved in obesity." (PMID 40289963, 2025). "Variants in TAS1R2 and TAS1R3 sweet taste receptor genes have previously been associated with changes in taste sensitivity to sugar, the excessive consumption of which is an established risk factor for obesity and chronic disease." (PMID 30060620, 2018). "Our findings implicate many genes previously associated with obesity (e.g. PTBP2, TMEM18, MYT1L, POU3F2, SIM1, SH2B1), and also identified other potentially relevant candidates including TAS1R3, ALOX5AP, and GAS6." (PMID 29441128, 2018). "Our results did not necessarily show a clear link between certain human phenotypes (higher sugar intake and/or higher sweet detection threshold) and the cellular response of associated SNPs, suggesting that TAS1R2 and TAS1R3 SNPs are probably not the only factors associated with obesity." (PMID 40289963, 2025). "Even though TAS1R3 and GNAT3 were not related to sweet perception in this review, a third sweet-related gene, TAS1R2, has been observed to be linked with sweet taste threshold and consumption of sweet food in individuals with obesity compared to individuals with normal weight." (PMID 32635385, 2020).
type 2 diabetes (4 papers, 2021 to 2025). "TAS1R3 is a putative therapeutic target to remediate islet defects associated with type 2 diabetes." (PMID 41438300, 2025). "Participant characteristics of people with Type 2 Diabetes Mellitus (mean ± SD), in the total cohort and by TAS1R3 rs307355 and TRPV1 rs4790522 genotypes, in an additive, recessive and dominant manner." (PMID 40680045, 2025). "Overall, our results suggest that TAS1R3 plays an essential role in GTPase signaling in islet β-cells adding to the growing list of proteins that play a vital role in islets as therapeutic targets in type 2 diabetes." (PMID 41438300, 2025). "Notably, the significant reduction of TAS1R3 mRNA and protein levels in human type 2 diabetes pancreatic islets, which could be replicated in otherwise healthy cells exposed to diabetogenic stimuli, indicates that the TAS1R3 deficit may be a consequence of diabetogenic stimuli." (PMID 41438300, 2025). "As Type 2 diabetes (T2D) is a condition concerning insulin malfunction and GLP-1 secretion is involved in insulin release, the role of TAS1R2+TAS1R3 in the disorder has been explored." (PMID 34835968, 2021).
diabetes (3 papers, 2024 to 2025). "Recent studies linked the expression of Tas1R3 to the western diet-induced impairment of the male reproductive system, as well as diabetes-induced exacerbation of lung infection." (PMID 41244562, 2025). "A different study found that TAS1R3-linked polymorphic genotypes with heterozygous, TC, alleles at rs307355 are related to strong sweet taste sensitivity and that diabetes had a higher preference for sweetness." (PMID 40680045, 2025). "In line with our observations, ER stress is increased in classical monocytes of patients with diabetes, which, as we showed here, express high amounts of Tas1R3." (PMID 41244562, 2025). "However, the role of Tas1R3 in shaping macrophage functionality and its contribution to the onset of diabetes and related complications remains elusive." (PMID 41244562, 2025). "This further demonstrates an important role of Tas1R3 in glucose-induced perturbations of immune cells in diabetes and highlights the necessity of continued in depth research to fully understand the role of Tas1R3 and the impact of artificial sweeteners on human health." (PMID 41244562, 2025). "Similarly, in the context of diabetes and hyperglycemia, Tas1R3 expression is upregulated in various tissues, including the intestine, the lung, and the testes." (PMID 41244562, 2025).
Impaired glucose tolerance (3 papers, 2015 to 2025). An abnormal resistance to glucose, i.e., a reduction in the ability to maintain glucose levels in the blood stream within normal limits following oral or intravenous administration of glucose. "Impaired glucose tolerance is usually associated with reduced insulin sensitivity, which was also demonstrated for Tas1r3-/- mice in our study." (PMID 26107521, 2015). "Here, we showed that human T2D islets displayed significantly reduced TAS1R3 levels compared with non-diabetic controls, consistent with the impaired glucose tolerance and insulin resistance phenotype observed in the TAS1R3 knockout mice." (PMID 41438300, 2025).
Insulin resistance (3 papers, 2023 to 2025). Increased resistance towards insulin, that is, diminished effectiveness of insulin in reducing blood glucose levels. "Nevertheless, these emerging mechanistic insights establish TAS1R3 as a future target to remediate skeletal muscle insulin resistance in prediabetes and T2D." (PMID 41515983, 2025). "This dysregulation hinders glucose uptake and contributes to muscle insulin resistance, underscoring the importance of pathways that intersect with TAS1R3-mediated signaling." (PMID 41515983, 2025). "Thus, larger cohorts are needed that consist of non-insulin-resistant, prediabetes (impaired fasting blood glucose and/or impaired insulin tolerance), and T2D patients to support the decline in TAS1R3 with the progression of insulin resistance." (PMID 41515983, 2025). "We showed that TAS1R3 mRNA and protein levels were depleted in T2D skeletal muscle, which was similarly observed in GLT-exposed human LHCN-M2 myotubes, which is used as a model for earlier stages of insulin resistance, suggesting that TAS1R3 levels are depleted in insulin-resistant muscle." (PMID 41515983, 2025).
Anxiety (1 paper, 2023). Intense feelings of nervousness, tension, or panic often arise in response to interpersonal stresses. "The findings from our rodent model confirmed that Tas1r3 deficiency prevents WD-induced neuronal loss and anxiety." (PMID 37926812, 2023). "The present study provides the first comprehensive description of the roles of TAS1R3 in the hypothalamus, providing additional evidence of causality between WD and anxiety and revealing the previously unexplained mechanism of WD-induced anxiety." (PMID 37926812, 2023). "Next, we investigated the implicit mechanism of WD-induced anxiety prevented by Tas1r3 deficiency by confirming the top significant canonical pathways by IPA (ingenuity pathway analysis)." (PMID 37926812, 2023). "Thus, we investigated the influence of excessive WD intake on anxiety and mechanisms by which WD intake affects anxiety development using wild-type (WT) and Tas1r3 deficient (Tas1r3−/−) mice fed a normal diet (ND) or WD for 12 weeks." (PMID 37926812, 2023). "However, despite the genetic similarity, further human studies are needed to investigate the association between TAS1R3 expression levels and anxiety status in people consuming Western diets." (PMID 37926812, 2023). "Ultimately, we displayed that TAS1R3 is a key regulator of nutritional stimulus-induced anxiety by altering hypothalamic function." (PMID 37926812, 2023). "WD increased anxiety in male WT mice, whereas male Tas1r3−/− mice were protected from WD-induced anxiety, as assessed by open field (OF), elevated plus maze (EPM), light–dark box (LDB), and novelty-suppressed feeding (NSF) tests." (PMID 37926812, 2023). "Our findings uncover the previously unknown role of TAS1R3 in the context of WD-induced anxiety-like phenotype and may contribute to the development of preventive or therapeutic strategies for anxiety disorders." (PMID 37926812, 2023). "Although recent studies have shown that nutrient-sensing receptors expressed in the hypothalamus modulate diet-induced mood disorders, the role of TAS1R3 in WD-induced anxiety remains unknown." (PMID 37926812, 2023). "In this context, we hypothesized that nutrient-induced modulation of hypothalamic TAS1R3 is central to the regulation of WD-induced anxiety." (PMID 37926812, 2023). "Furthermore, bioinformatic analysis revealed that the CREB/BDNF signaling-mediated maintenance of neuronal regeneration, which can prevent anxiety development, was enhanced in WD-fed Tas1r3−/− mice compared with WD-fed WT mice." (PMID 37926812, 2023). "The molecular mechanisms by which TAS1R3 regulates anxiety remain unclear." (PMID 37926812, 2023). "Considering that the anxiety levels of WD-fed male WT and Tas1r3-/- mice were not explained by their body weight, we investigated the underlying molecular mechanisms in the hypothalamus, a brain structure primarily involved in anxiety." (PMID 37926812, 2023). "However, Tas1r3-/- mice were protected from the WD-induced anxiety." (PMID 37926812, 2023). "Our results imply that TAS1R3 may play a key role in WD-induced alterations in hypothalamic functions, and that inhibition of TAS1R3 overactivation in the hypothalamus could offer therapeutic targets to alleviate the effects of WD on anxiety." (PMID 37926812, 2023). "However, WD-fed male Tas1r3-/- mice didn’t exhibit WD-induced anxiety-behaviors." (PMID 37926812, 2023). "In contrast, in our model, in which Tas1r3 deficient mice were fed WD for 12 weeks, Tas1r3 deficiency-mediated neuroprotective effects in the hypothalamus of WD-fed mice reduced WD-induced immobility and anxiety-like behaviors, but there were no behavioral changes in ND-fed mice." (PMID 37926812, 2023). "Abundant expression of taste receptor type 1 member 3 (TAS1R3) has been identified in the hypothalamus, a key brain area involved in sensing peripheral nutritional signals and regulating anxiety." (PMID 37926812, 2023).
Anxiety (continued). "Additionally, TAS1R3 is a GPCR, which is a major therapeutic target for approved drugs, suggesting that it could be a novel therapeutic target for diet-induced anxiety." (PMID 37926812, 2023).
breast carcinoma (1 paper, 2018).
cervical squamous cell carcinoma (1 paper, 2022). A squamous cell carcinoma arising from the cervical epithelium. "Notably, statistically significant survival associations were identified for TAS2R5 in cervical squamous cell carcinoma (p < 0.001), TAS2R20 in esophageal adenocarcinoma (p = 0.044), and TAS2R4, TAS2R20, and TAS1R3 in prostate adenocarcinoma (p = 0.03, p = 0.033, and p = 0.023, respectively)." (PMID 35624283, 2022).
colitis (1 paper, 2023). Inflammation of the colon. "We also assessed the effects of Tas1r3 deficiency on the development of intestinal inflammation in a DSS-induced colitis mouse model." (PMID 37118698, 2023). "Taken together, these findings indicate that the severity of DSS-induced colitis was significantly decreased in Tas1r3−/− mice, suggesting that TAS1R3 deficiency alleviates intestinal inflammation." (PMID 37118698, 2023). "In addition to the WD-induced inflammation model, Tas1r3 deficiency suppressed intestinal inflammation in a DSS-induced colitis model." (PMID 37118698, 2023). "Furthermore, it might be needed for future work to look at how microbial changes in Tas1r3-deficient mice can affect colitis susceptibility by transferring altered microbial contents to germ-free or antibiotic mice." (PMID 37118698, 2023).
COVID-19 (1 paper, 2024). A disease caused by infection with severe acute respiratory syndrome coronavirus 2. "Statistical analyses detected significant associations between rs307355 of the TAS1R3 gene and the following COVID-19-related symptoms: chest pain and shortness of breath." (PMID 38398728, 2024). "Two statistically significant associations between rs307355 of the TAS1R3 gene and COVID-19 symptom severity were detected." (PMID 38398728, 2024). "Concerning the second aim, both logistic and ordinal regression models allowed the identification of two statistically significant positive associations between rs307355 of the TAS1R3 gene and two COVID-19-related symptoms: (i) chest pain and (ii) shortness of breath." (PMID 38398728, 2024).
dental caries (1 paper, 2022). The decay of a tooth, in which it becomes softened, discolored, and/or porous. "TAS1R3 gene rs307355 polymorphism has been found to be an independent risk factor for dental caries experience and to have increased the risk of caries." (PMID 35425718, 2022).
leukemia (1 paper, 2014). A malignant (clonal) hematologic disorder, involving hematopoietic stem cells and characterized by the presence of primitive or atypical myeloid or lymphoid cells in the bone marrow and the blood. "The candidates ATP2B2, PARP8 and TAS1R3 have previously not been functionally linked to leukemia." (PMID 24517546, 2014).
myocardial hypertrophy (1 paper, 2025). "Therefore, in myocardial hypertrophy, tRF-Glu-CTC-013 targets and inhibits Tas1r3, thereby promoting autophagy and attenuating inflammation, myocardial hypertrophy and fibrosis." (PMID 40520901, 2025).
Splenomegaly (1 paper, 2023). Abnormal increased size of the spleen. "However, splenomegaly, which indicates increased systemic inflammation, was observed in WD-fed Tas1r3+/+ but not in WD-fed Tas1r3−/− mice." (PMID 37118698, 2023).
viral infections (1 paper, 2024). "To date, no studies have described TAS1R3 gene function in regulating immune response or determining viral infection symptom severity in the human lower respiratory tract." (PMID 38398728, 2024).
tumor (3 papers, 2022 to 2025). "Changes in expression for TAS1R1, TAS1R3, TAS2R4, TAS2R5, TAS2R14, TAS2R19, and TAS2R20 had survival associations in at least one tumor histology." (PMID 35624283, 2022). "In particular, genes such as MTND1P23, PLCH2, RNF223, PERM1, TAS1R3, and specific TMEM genes exhibit varied levels of expression across different tumour stages, thereby presenting a potential to discern early-stage ESCC from its later stages." (PMID 38562378, 2024). "Across all tumor types, the median percentage of tumors with nonsilent mutations in TAS1Rs, including TAS1R1, TAS1R2, TAS1R3, was slightly less than 1%." (PMID 35624283, 2022).
TAS1R3 also shares sentences with these, for which no sentence is quoted: cancer (2 papers); Hepatic steatosis (2); metabolic disease (2); metabolic syndrome (2); Alcohol Use Disorders (1); eosinophilia (1); esophageal adenocarcinoma (1); Glucose intolerance (1); head and neck cancer (1); Hyperglycemia (1); Hyperinsulinemia (1); infection (1); Infertility (1); inflammation (1); kidney clear cell carcinoma (1); morbid obesity (1); nonalcoholic fatty liver disease (1); prediabetes (1); prostate adenocarcinoma (1); steatosis (1); stomatitis (1).